S100B (S100 calcium binding protein B)
Diseases named in the same sentence as S100B in open-access papers (continued):
Sharing a sentence is not in itself a finding about the gene and the disease.
intracranial hemorrhage (continued). "Specifically, its high sensitivity allows serum S100B under the cutoff value (0.10 μg/L), when determined within 6 h following trauma, to rule out serious traumatic intracranial hemorrhage in adult patients with mild head injury and without other risk factors." (PMID 37474905, 2023). "The performance of S100B is similar to that shown by previous studies and indicates that even though it correctly classifies most patients with intracranial hemorrhage, it is not perfect." (PMID 31089789, 2021). "The primary aim was to evaluate the ability of urine S100B to rule out intracranial hemorrhage in patients with head trauma." (PMID 31388712, 2021). "The difference in the urine S100B levels between patients with and without intracranial hemorrhage is small, and the difference in their serum S100B levels is larger." (PMID 31388712, 2021). "The results of this study indicate that correlation and agreement between capillary and venous samples are low, and because of this, we cannot recommend studies on capillary serum S100B protein level to rule out intracranial hemorrhage in mTBI." (PMID 31477027, 2019). "Age and gender matching between healthy volunteers and patients with intracranial hemorrhage was not performed as it was only the serum S100B protein levels that were relevant to this study and not the specific patient traits." (PMID 31477027, 2019). "The median serum S100B protein level of 0.08 μg/l in patients with intracranial hemorrhage was close to the median value (0.07 μg/l) of patients without intracranial hemorrhage." (PMID 31477027, 2019). "The Scandinavian Neurotrauma Committee guideline uses serum S100B protein level to rule out intracranial hemorrhage." (PMID 31477027, 2019). "Furthermore, evidence suggests that levels of GFAP and S100β could distinguish between AIS and brain hemorrhage." (PMID 35813155, 2022). "Furthermore, no studies have investigated the temporal profile of urine S100B in adults with intracranial hemorrhage, and elevated levels can possibly be detected in urine longer than in serum." (PMID 31388712, 2021). "However, neither urine S100B nor the arithmetic difference can be recommended as a biomarker for intracranial hemorrhage in the clinical setting, because the sensitivity is too low." (PMID 31388712, 2021). "The urine S100B of a patient with head trauma but who does not have an intracranial hemorrhage might reflect this first S100B surge." (PMID 31388712, 2021). "The present study does not support using urine S100B to rule out intracranial hemorrhage." (PMID 31388712, 2021). "The results of this study indicate that correlation and agreement between capillary and venous samples are low, and because of this, we cannot recommend studies on capillary serum S100B protein level to rule out intracranial hemorrhage in mild traumatic brain injury." (PMID 31477027, 2019). "Given the limitations of the current sampling and analysis methods of capillary protein S100B protein level, we conclude that evaluating its predictive ability to rule out intracranial hemorrhage should be withheld until more reliable methods can be incorporated into the study design." (PMID 31477027, 2019). "This can in part be explained by the fact that the patients with intracranial hemorrhage were not always sampled within 6 h of trauma and were sampled over several days which could have led to a normalization in serum S100B protein levels." (PMID 31477027, 2019).
infarction (17 papers, 2006 to 2025). A localised pathological necrosis of tissue resulting from obstruction of the blood supply usually by a thrombus, an embolus, or vascular torsion. "In the resource-limited setting, assessment of injury may rely on a single marker; S100B is promising—an increase between admission and week 2 was associated with infarct severity and also strongly predicted mortality." (PMID 28605426, 2017). "The results of the statistical analysis show that the serum levels of sTREM-1 and S100B were significantly higher in the large-infarction group than in the control group and small-infarction group." (PMID 33375339, 2020). "It has been postulated that S100B is a marker signaling irreversible ischemic damage, thus explaining its correlation with infarction and subsequent worse long-term prognosis." (PMID 27007976, 2016). "S100B is induced in peri-infarct myocytes postmyocardial infarction in human subjects and experimental rodent models of myocardial infarction and in response to α1-adrenergic stimulation." (PMID 20672023, 2010). "The results from this study, in agreement with our study, confirmed that elevated serum S100β values after subarachnoid aneurismal hemorrhage correlate with postoperative CT scan findings such as infarction and vasospasm." (PMID 17020600, 2006). "When mean S100B levels were then dichotomized based on secondary complications (infarction or early rebleeding), secondary increase was found to be exclusively related to infarction." (PMID 33172087, 2020). "It was found that serum levels of S100B, S100A6, and S100P are associated with ischemic myocardial injury in acute coronary syndrome (ACS), and expression of these S100 proteins is related to myocardial infarct size." (PMID 33614740, 2020). "Cardiomyocytes do not express S100B in normal physiological conditions; however, S100B becomes expressed in cardiomyocytes surviving an infarction under the action of catecholamines and acts to inhibit the cardiomyocyte hypertrophic response with a mechanism that remains to be elucidated." (PMID 20827421, 2010). "Thus, it is not surprising that GOS outcome has an association with S100B, which is correlated with infarction itself." (PMID 27007976, 2016). "Cardiomyocytes do not express S100B, but S100B becomes expressed in the cardiomyocytes surviving an infarction under the action of catecholamines." (PMID 20827421, 2010). "This may be because S100β level is only related to infarction volume, not infarction location, while the neurological scores (e.g., NIHSS and mRS scores) are affected by location." (PMID 39358745, 2024). "A previous study found that early rebleeding was associated with poor neurological outcome but not with in-hospital mortality, and could suggest that rebleeding may not be responsible for sufficient brain cell damage to release S100B protein in the serum, unlike infarction." (PMID 33172087, 2020).
Hypertension (16 papers, 2016 to 2025). The presence of chronic increased pressure in the systemic arterial system. "Logistic regression analysis revealed that a high serum S100β proteinlevel, hypertension, and high low density lipoprotein-cholesterol (LDL-C) level werethe independent risk factors for SVD." (PMID 28143956, 2017). "Patients were divided into normal blood pressure group (n=62)and hypertension group (n=100) based on their blood pressure,and their serum S100β level was compared and analyzed." (PMID 28143956, 2017). "In addition, hypertension patients showedhigher S100β levels than those with normal blood pressure and the normalcontrol group, and there was a positive correlation between S100β level andblood pressure." (PMID 28143956, 2017). "In addition, an increased S100β level could beseen in SVD patients with hypertension in comparison with those with normal bloodpressure." (PMID 28143956, 2017).
metastatic melanoma (16 papers, 2013 to 2025). A melanoma that has spread from its primary site to another anatomic site. "Serum S100B levels correlate with aggressive disease and have been shown to be a reliable prognostic marker in metastatic melanoma." (PMID 39272837, 2024). "In our study, we found that elevated baseline serum S100B levels were associated with a higher risk of progression and death compared with normal baseline serum S100B levels in BRAF V600 mutant metastatic melanoma patients treated with BRAF + MEK inhibitors." (PMID 39272837, 2024). "Another marker worth mentioning is serum S100B, which is a routinely monitored laboratory parameter in patients with metastatic melanoma." (PMID 39272837, 2024). "Next, we treated S100b-suppressed F1 and F10 cells with chemotherapeutic agents against metastatic melanoma: cisplatin, a platinum analog, and tunicamycin, an inducer of endoplasmic reticulum stress." (PMID 36899866, 2023). "Due to the distribution pattern and elevated serum tumor marker S100B, metastatic melanoma was considered." (PMID 33928039, 2021). "Combined use of tumor type M2 pyruvate kinase (PKM2) and S100β improves the estimation of disease prognosis in metastatic melanoma patients, compared to the use of S100β alone." (PMID 31803364, 2019). "Our study suggests that clinicopathological factors, including primary tumor characteristics, stage of metastatic disease, and serum LDH and S100B, can be used in the prognostic stratification of metastatic melanoma patients treated with BRAF and MEK inhibitors." (PMID 39272837, 2024). "In this retrospective study the prognostic performance of demographic data, clinical and histological prognostic markers and baseline serum LDH and S100B levels were tested in metastatic melanoma patients treated with anti-PD-1 using Cox regression and Kaplan-Meier survival analyses." (PMID 37664072, 2023). "Serum S100B levels have been reported to monitor response to immunotherapy in metastatic melanoma." (PMID 37468850, 2023). "Especially S100B has proven its usefulness in monitoring metastatic malignant melanoma." (PMID 32188047, 2020). "The role of S100B to select patients for treatment and to predict prognosis should be investigated in future studies in patients treated with new and more potent drugs in metastatic melanoma." (PMID 24312329, 2013). "Some studies suggest that S100B may surpass LDH in predicting OS in metastatic melanoma." (PMID 39766118, 2024). "Furthermore, research on metastatic melanoma with elevated serum S100B and LDH levels may provide a step forward to improve treatment efficiency." (PMID 37664072, 2023). "Importantly, the active role of extracellular S100B in neuroinflammation was revealed, and through similar processes, S100B may play a role in the progression of metastatic melanoma, contributing to the unfavourable outcome of the disease." (PMID 37664072, 2023). "In 2011, a study was published comparing the significance of S100B and PET-CT in patients with a metastatic melanoma." (PMID 38202181, 2023). "Serum S100B and LDH levels are routinely monitored in patients with metastatic melanoma in cancer centers." (PMID 37664072, 2023). "In retrospective studies performed among metastatic melanoma patients treated with anti-PD-1, anti-CTLA-4 or anti-CTLA-4+anti-PD-1 the baseline serum S100B level proved to be independent predictor of primary resistance to therapy and overall survival." (PMID 37664072, 2023). "Serum S100B and LDH are thought to correlate with tumour volume and necrosis in metastatic melanoma." (PMID 37664072, 2023).
colitis (15 papers, 2012 to 2024). Inflammation of the colon. "For the first time, we showed that S100B is also elevated during CDI in humans and in mice, suggesting that reactive gliosis, indeed, occurs in C. difficile–associated colitis." (PMID 34568098, 2021). "In this models, PEA anti-inflammatory effects were also closely related to the specific reduction of enteric glial cells (EGCs) activation during colitis, mediated by the selective targeting of the S100B/TLR4 axis." (PMID 33986673, 2021). "In line, we observed an increase in S100β expression in PLP1-positive cells within the myenteric plexuses of DNBS rats that persisted until day 7 from colitis induction." (PMID 34829900, 2021). "Pentamidine exerts a marked anti-inflammatory effect in a mice model of acute colitis, likely targeting S100B activity." (PMID 23259641, 2012). "Similarly, in the animal model of acute colitis induced by dextran sodium sulfate, high levels of S100B were described, while macroscopic and histological/biochemical assays of colonic tissues and plasma revealed a significant amelioration after treatment with PTM, the inhibitor of S100B activity." (PMID 37298554, 2023). "Immunofluorescence analysis revealed a significant increase in S100β (102.11% vs. vehicle) and TRPV1 (+89.45% vs. vehicle) in the DRG of DNBS-treated rats compared to the vehicle group on day 7 after colitis induction (p < 0.0001)." (PMID 34829900, 2021). "According to our previous results, obtained in an experimental model of colitis, PEA was able to dampen EGC activation and the consequent overexpression of S100B and iNOS protein in the submucosal plexus isolated from colon." (PMID 29573741, 2018). "Given recent work on the neurogenic potential of EGCs52,59, it is notable that we saw upregulation of the canonical glial markers GFAP and S100β specifically in cured mice, as well as PLP1, which corresponds to the subset of glial cells that differentiate into neurons in the DSS colitis model." (PMID 38782898, 2024). "Altered expression of S100B and GFAP has been reported in several intestinal inflammatory disorders in humans, such as inflammatory bowel disease, celiac disease, and postoperative colitis." (PMID 37834076, 2023). "Similarly in PLP1CreER:tdT mice, PLP1 cells that co-express S100b but not RET also give rise to neurons following colitis." (PMID 28566702, 2017).
hemorrhagic stroke (14 papers, 2012 to 2025). A stroke caused by a bleed on the brain. "This meta-analysis showed only S100β and copeptin are of high certainty to serve as prognosticators for hemorrhagic stroke patients." (PMID 39970158, 2025). "S100B has been shown to be a reliable marker for cerebral injury in many settings including traumatic brain injury and ischemic as well as hemorrhagic stroke." (PMID 36747206, 2023). "Other proteins studied previously in hemorrhagic stroke, such as S100B and GFAP, are mainly expressed by astrocytes, macroglial cells that play an important role in the regulation of blood-brain barrier." (PMID 23049835, 2012). "For instance, elevated S100B protein levels are associated with worse outcomes, while markers like D-dimer, CRP, and NSE assist in distinguishing between ischemic and hemorrhagic strokes, as well as gauging event severity, corroborating studies by Jickling and Kamtchum-Tatuene." (PMID 41173049, 2025).
migraine (14 papers, 2017 to 2025). "In migraine, elevated levels of S100β in blood have been proposed as a diagnostic biomarker." (PMID 41515906, 2025). "The subgroup analyses by age, country, migraine assessment, and assay method of S100B also illustrated a statistically obvious association between S100B levels and migraine, indicating that age may be the most important source of heterogeneity." (PMID 35911929, 2022). "Migraine may be associated with pathological reactions involving S100B, which is instrumental for the clinical diagnosis of migraine and therapy that considers S100B as a potential target." (PMID 35911929, 2022). "Altered S100B level was also documented in other pain conditions, including fibromyalgia and migraine." (PMID 38671372, 2024). "The combined results of nine case–control studies indicated that compared with healthy controls, overall migraine patients had significantly increased S100B levels in peripheral blood (SMD = 0.688, 95% CI: 0.341–1.036, P < 0.001)." (PMID 37932721, 2023). "Relatively more clinical data on S100B in migraine are available; however, its status remains inconclusive." (PMID 36835524, 2023). "It has been previously reported that increase in CSF S100B levels with age is higher in men than women undergoing surgery, in contrast to which, a study in migraine patients found that serum S100B was higher in females than males." (PMID 32379790, 2020). "In migraine patients, serum S100B levels were elevated during a migraine attack as compared to healthy subjects, although maximum concentrations were observed during the pain-free period post migraine attack." (PMID 32379790, 2020). "However, the results regarding glial biomarkers, like the S100B protein, are controversial in migraine." (PMID 36835524, 2023). "Therefore, the use of NSE and S100B as biomarkers for determining the presence of neurological damage in migraine remains to be further investigated." (PMID 37932721, 2023). "In contrast, a case–control study indicated that interictal serum S100B levels are not elevated in migraine patients." (PMID 37932721, 2023).